CRP (C-reactive protein)
Diseases named in the same sentence as CRP in open-access papers (continued):
Sharing a sentence is not in itself a finding about the gene and the disease.
neutropenia (continued). "On day 7 of the first course, the patient exhibited a fever of 37.9°C, neutropenia (519/μL), and elevated inflammatory markers (C reactive protein [CRP] 16.91 mg/dL), leading to a diagnosis of febrile neutropenia." (PMID 38528720, 2024). "Blood tests showed neutropenia (60/μL) and elevated inflammatory markers (CRP 26.23 mg/dL), leading to a diagnosis of recurrent febrile neutropenia." (PMID 38528720, 2024). "Blood work during the attacks revealed leukopenia (1800–2000 cells/mm3) with neutropenia (180/mm3) and elevated C‐reactive protein (CRP) (180 mg/L)." (PMID 37647436, 2023). "By further multivariate analysis, CRP [OR (95% CI): 1.022(1.003, 1.041), p = 0.021] and neutropenia [OR (95% CI): 21.634 (2.05, 228.313, p = 0.011] within 24 h of infection were independent risk factors for death in children with AB bacteremia." (PMID 37775747, 2023). "After COX regression correction, CRP (OR (95% CI): 1.022(1.003, 1.041), p = 0.021) and neutropenia (< 1.5 × 109/L) (OR (95% CI): 21.634 (2.05, 228.313, p = 0.011) within 24 h of infection were the independent risk factor for death in children with AB-BSI." (PMID 37775747, 2023). "In conclusion, parameters such as sex, neutropenia, aPTT prolongation, and normal CRP levels were identified, which can be easily assessed in the emergency room." (PMID 37100782, 2023). "In a previous study, the neutropenia group had higher PCT and CRP levels than the non-neutropenia group, considering patients with hematologic malignancies." (PMID 37046430, 2023). "SAA exhibited comparable performance to PCT, DNI, and CRP and can be deemed a good biomarker for diagnosing infection in all patients and those with neutropenia." (PMID 37046430, 2023). "Blood analysis at hospitalization showed neutropenia (absolute count neutrophils was 497/mm3) and CRP of 342 mg/L." (PMID 38031167, 2023). "The model constructed in this study was LogitP = −3.744 + 1.387 × (hormone use) + 2.011 × (neutropenia or agranulocytosis) + 1.185 × (Hb < 90 g/L) + 1.180 × (CRP > 15 mg/L)." (PMID 35601429, 2022). "The secondary aim was to evaluate the potential of CRP in the diagnosing requirement of antimicrobial treatment due to SIRS or neutropenia in AHDS upon admission." (PMID 36713872, 2022). "In the present study, the CRP values in the severe neutropenia and non-neutropenia groups were 0.43 ± 1.10 mg/dL and 0.89 ± 1.57 mg/dL, respectively." (PMID 34260659, 2021). "According to previous reports, elevated CRP level and severe neutropenia are significantly correlated with worse survival." (PMID 34356952, 2021). "CRP in neutropenia Grade 0–2 was higher than that in Grade 3/4 (Grade 0–2: 0.28 mg/dL, Grade 3/4: 0.10 mg/dL)." (PMID 34260659, 2021). "We investigated the diagnostic and predictive role of PCT and PSPN in comparison to CRP in 60 patients with neutropenia acute leukemia at the onset of febrile neutropenia." (PMID 34324506, 2021). "In all the cases, white blood cell count, neutropenia, lymphocytes, and C-reactive protein were normal." (PMID 33569363, 2020). "His family physician advised that he continue using antibiotics; however, progressive neutropenia and an increased CRP level were shown." (PMID 31931763, 2020). "On the other hand, higher mortality was linked with age > 70 years, uncontrolled hematological malignancy, baseline poor performance status, baseline severe neutropenia and a high CRP." (PMID 32864192, 2020). "This is consistent with the course of neutropenia and coincides with the CRP peak, affirming previous studies on OM during HSCT." (PMID 31993753, 2020). "Patients with severe IGASI more commonly had abnormal respiratory symptoms, neutropenia, and a higher CRP level (p < 0.05) compared to the other patients." (PMID 32435626, 2020). "An 11-month-old boy who had received three doses of PCV-13 was hospitalized with prolonged fever, bilateral otitis media, neutropenia and elevated C-reactive protein (CRP) levels." (PMID 31931763, 2020).
neutropenia (continued). "Serial trends in C-reactive protein and certain other inflammatory cytokines demonstrated a corresponding rise at the time of neutropenia." (PMID 31277704, 2019). "A significant reduction in WBC count with neutropenia was also observed along with a delayed initiation of CRP response." (PMID 29471782, 2018). "CRP has traditionally been used to evaluate the severity of infection and also the response to antimicrobial therapy in patients with febrile neutropenia, even though its predictive value is controversial." (PMID 23634180, 2013). "• In the present study we showed that septic cancer patients express a full blown acute phase response with marked CRP elevations, and that this was particularly significant in the presence of neutropenia." (PMID 21595932, 2011). "In septic critically ill cancer patients CRP concentrations are more elevated in those with neutropenia." (PMID 21595932, 2011). "It was clear from our results that septic cancer patients express a full blown acute phase response with marked CRP elevations, and that this was particularly significant in the presence of neutropenia." (PMID 21595932, 2011). "The impact of neutropenia on CRP concentrations at admission and during the first week of ICU stay was assessed." (PMID 21595932, 2011). "The neutropenia initially corrected and the erythrocyte sedimentation rate and C-reactive protein improved significantly." (PMID 19946450, 2009). "Laboratory studies showed a hemoglobin of 8.9 g/dl, a total white cell count of 2.9 × 109/μl, with a neutropenia 0.9 × 109/μl, C reactive protein (CRP) 266 and blood glucose 6.4 (units)." (PMID 20181146, 2009). "PCT concentration was markedly associated with the diagnosis of severe infection in patients with febrile neutropenia, in contrast with CRP whose concentration was so useful to distinguish between presence and absence of a disseminated infection." (PMID 18034890, 2007). "We found that the frequency of neutropenia was high in the CRP-normal group, whereas no other associations were observed between the frequency of other side effects and CRP, LDH, or Alb levels." (PMID 38965074, 2025). "PCT has consistently demonstrated superior performance over CRP in distinguishing infectious from non-infectious causes of fever in children with neutropenia." (PMID 40647525, 2025). "However, in a multivariate analysis where CRP was included as a variable, the group with severe neutropenia showed a significantly better or more favorable trend compared to the group with non-severe neutropenia." (PMID 39870769, 2025). "This suggest that neutropenia contributes to the therapeutic effect independently of CRP." (PMID 39870769, 2025). "Elevated levels of both CRP and PCT were associated with an increased risk of BSI in univariate analyses, but only PCT remained significant in multivariate analyses adjusting for sex, age, neutropenia, and diagnosis." (PMID 37919603, 2024). "Recent findings have highlighted the high rate of breakthrough invasive aspergillosis among patients receiving caspofungin for persistent fever and neutropenia, underscoring the need for vigilant monitoring and possibly adjusting antifungal therapy based on CRP levels and other biomarkers." (PMID 39720656, 2024). "Sex, especially the male (odds ratio [OR] 11.45, P = 0.012), neutropenia (< 1500) (OR 41.64, P ≤ 0.001), aPTT prolongation (> 35 s) (OR 80.133, P ≤ 0.001), and normal CRP concentration (≤ 1.0 mg/dL; OR 166.855, P = 0.001) were significantly associated with SFTS but not HGA." (PMID 37100782, 2023). "Therefore, we chose CRP (>10 mg/l) accompanied with severe neutropenia (ANC <0.5 × 109/l) as the primary endpoint." (PMID 34859963, 2022). "This novel concept may support the results of this study, in which ED-treated patients tended to have reduced neutropenia, decreased inflammation of mucosa, and lower CRP levels." (PMID 34626918, 2021).
neutropenia (continued). "Half of patients were considered as affected by a severe disease and exhibited more commonly respiratory disorders, neutropenia, and high CRP level and needed more transfusion and longer duration of antibiotics and length of stay compared to the patients with non-severe IGASI." (PMID 32435626, 2020). "On the other hand, in older populations with cancer and neutropenia, CRP levels rise with infection and may be higher in patients with neutropenia compared to those without." (PMID 24244325, 2013). "Repeated negative cultures of blood samples, the application of antibiotics adapted to the strains cultured in other samples, low concentrations of CRP, and normal or even lowered leukocyte count (together with lympho- and neutropenia) seem to contradict this hypothesis." (PMID 35887970, 2022). "Although T-Bil and CRP have not been previously reported as risk factors for Grade 3/4 neutropenia in GnP therapy, our results suggest that close monitoring of adverse events is important even in patients whose clinical laboratory values are within the reference ranges." (PMID 34260659, 2021). "Previous attempts to find a correlation between higher CRP or WBC count and disease severity in NEC have been hampered, but there is a scale to assess the severity of NEC, which uses WBC count and base excess as predictors, thus treating neutropenia and low base excess as additional risk factors." (PMID 30406064, 2018). "We present the case of an eight-day-old, full-term female infant who presented with fever and irritability, later diagnosed with severe neutropenia (ANC: 400/μL) and elevated C-reactive protein (CRP) (150 mg/L)." (PMID 41695004, 2026). "In our case, the patient had persistent fever, abnormal CRP and PCT values, and neutropenia; therefore, a decision was made to extend the diagnostics towards IFI." (PMID 39338963, 2024). "The mean C-reactive protein (CRP) was 144 mg/dl, and the mean white cell count (WCC) was 11.4 × 109/L (neutropenia 27/75, 36%)." (PMID 38205482, 2023). "Still in severe neutropenia, IPF% was the first parameter that significantly increased and anticipated the CRP peak (11.9 ± 1.6 days, mean ± SD)." (PMID 36849723, 2023). "CRP and procalcitonin (PCT) were directly correlated with the degree of neutropenia and inversely correlated with total leucocyte count (TLC)." (PMID 36923173, 2023). "The gender, age, neutropenia, specimen distribution, CMT, and mNGS positivity; CRP, PCT, IL-6, and IL-10 levels; and the agreement rate of mNGS with clinic were all comparable between the two groups." (PMID 35391735, 2022). "The concentration of CRP, PCT and chemokines was determined during the first hour of fever and 12–24 h afterwards in pediatric oncology patients with neutropenia." (PMID 36670590, 2022). "Her raised inflammatory markers (CRP 16-71 mg/l, ESR 10-160 mm/hr) and neutropenia (0.7–2 × 109/l) also persisted." (PMID 35840971, 2022). "There are few studies that analyzed together the kinetics of CRP, PCT and IL-6 in pediatric patients with fever and neutropenia and to our knowledge this is the first study that describes MR-proADM kinetics with the rest of them." (PMID 34828740, 2021). "Patients with neutropenia were younger, had lower levels of initial ANC, white blood cell (WBC) count and C-reactive protein (CRP)." (PMID 34150684, 2021). "Elevation in C-reactive protein (CRP) with neutropenia and subsequent fall with neutropenia resolution was a unique observation in our patient." (PMID 31277704, 2019). "The maximum temperature, CRP, duration of G-CSF, duration of FN, and duration of recovery from neutropenia used at the time of hospitalization were not significantly different in both groups." (PMID 41479552, 2025). "At the onset of fever, CRP levels were slightly increased in BSI episodes compared to non-BSI-related febrile episodes (22.0 mg/l (1.0–295) vs. 14 mg/l (1.0–305), p = 0.045), but this was insignificant for the subgroup with concurrent neutropenia." (PMID 37919603, 2024).
neutropenia (continued). "In the absence of neutropenia, both PCT and CRP demonstrated high diagnostic accuracy (AUC, 0.757 vs. 0.763, respectively)." (PMID 39283042, 2024). "Second, laboratory results, such as neutropenia and C-reactive protein (CRP) levels, were not included in the nomogram model owing to the study design." (PMID 37898771, 2023). "CRP values in the severe neutropenia and non-neutropenia groups were 0.43 ± 1.10 mg/dL and 0.89 ± 1.57 mg/dL, respectively." (PMID 34260659, 2021). "Infants without neutropenia showed age <3 months at onset in 34%, C-reactive protein level <1.0 mg/L in 27%, and nasopharyngeal microbiota composition with any of Moraxella catarrhalis, Streptococcus pneumoniae, or Haemophilus influenzae in 63%." (PMID 33671944, 2021). "In their study, the CRP (mean ± SE) was 2.46 ± 0.06 mg/dL in patients with severe neutropenia or febrile neutropenia and 1.29 ± 0.17 mg/dL in patients without severe neutropenia or febrile neutropenia." (PMID 34260659, 2021). "Procalcitonin (PCT), C-reactive protein (CRP), and neutrophil-to-lymphocyte ratio (NLR) have emerged as important markers of inflammation, and these markers, especially PCT and CRP, have been studied in patients with neutropenia." (PMID 32908505, 2020). "Studies have found that CRP changes were not influenced by neutropenia in septic patients, but CRP was not a good predictor of infection in neutropenic patients." (PMID 24772418, 2014). "In the present study, our aim was to assess in septic cancer patients the concentrations of a widely used biomarker of infection, CRP, comparing the baseline concentrations and response to antibiotic therapy in those with and without neutropenia." (PMID 21595932, 2011). "• The CRP course during the first week of antibiotic therapy was not influenced by the presence or absence of neutropenia." (PMID 21595932, 2011). "Among neutropenic patients, CRP concentrations at ICU admission were not influenced by the severity of neutropenia (< 100/mm3 vs. ≥ 100/mm3 neutrophils), 25.1 ± 11.6 mg/dL vs. 26.9 ± 10.9 mg/dL (P = 0.527)." (PMID 21595932, 2011). "To date, this is the first study comparing CRP concentrations in septic cancer patients with and without neutropenia, and with a large cohort of septic neutropenic patients." (PMID 21595932, 2011). "Laboratory workup revealed raised ESR and CRP during every episode without neutropenia." (PMID 41425676, 2025). "However, we found that the PCT and CRP levels were similar in patients with and without neutropenia with infection." (PMID 37046430, 2023). "However, in patients without neutropenia, SAA exhibited considerably higher diagnostic performance than PCT (p = 0.0018), CRP (p = 0.0451), and DNI (p = 0.0008)." (PMID 37046430, 2023). "Regarding the risk stratification, the patient status (age, degree and duration of neutropenia, colonizing microbial flora, CVC), the therapeutic approach (dose intense and time of chemotherapy) and the characteristics of the episode (fever, blood pressure, CRP) are of major concern." (PMID 32824956, 2020). "PCT and CRP levels were further analyzed between the presence and absence of neutropenia." (PMID 31821331, 2019). "Hence, the baseline serum levels of CRP in non-febrile patients of leukaemia were measured and compared with the levels after the onset of fever in patients with neutropenia." (PMID 23634180, 2013). "Additionally, among neutropenic patients CRP concentrations at ICU admission were not influenced by the severity of neutropenia (< 100/mm3 vs. ≥ 100/mm3 neutrophils), 25.1 ± 11.6 mg/dL vs. 26.9 ± 10.9 mg/dL, respectively (P = 0.527)." (PMID 21595932, 2011). "Second, clinical and laboratory data assessing the recovery phase of neutropenia and factors that could have influenced the CRP course were not routinely collected." (PMID 21595932, 2011).
neutropenia (continued). "Consequently, our findings pointed to the clinical usefulness of CRP in critically ill septic cancer patients irrespective of the presence or absence of neutropenia, as well as, the degree of neutropenia." (PMID 21595932, 2011). "Younger age at onset, lower C-reactive protein level, and less frequent identification of any of Moraxella catarrhalis, Streptococcus pneumoniae, or Haemophilus influenzae in nasopharyngeal aspirates were observed in infants with neutropenia, compared to those without neutropenia." (PMID 33671944, 2021). "Finally, CRP course was not influenced by the presence or absence of neutropenia." (PMID 21595932, 2011). "However, the CRP course seems to be independent from the presence or absence of neutropenia." (PMID 21595932, 2011). "By contrast, in group N (neutropenia and febrility without confirmed infection), PSP correlated with PCT (r = 0.631; p = 0.028), and CRP correlated with PCT to some measure (r = 0.564; p = 0.056)." (PMID 40217689, 2025). "In group I (neutropenia, febrility, and confirmed infection), a strong correlation was found between PSP and PCT (r = 0.638; p = 0.008), but not with CRP (r = 0.361; p = 0.090)." (PMID 40217689, 2025). "Our aim was to assess C-reactive protein (CRP) concentration in septic critically ill cancer patients and to compare those with and without neutropenia." (PMID 21595932, 2011). "Inflammatory markers (CRP and ESR) were elevated during each episode and there was no neutropenia." (PMID 41425676, 2025).